MSLN (mesothelin)
Diseases named in the same sentence as MSLN in open-access papers (continued):
Sharing a sentence is not in itself a finding about the gene and the disease.
ovarian carcinoma (continued). "We have recently described a predictive/prognostic model for ovarian cancer, exploiting commonly available clinico-pathological parameters and the ovarian serum biomarkers mesothelin (MSL), human epididymis protein 4 (HE4) and cancer-antigen 125 (CA125)." (PMID 39077473, 2024). "The MSLN CAR‐iNK cells effectively eliminate MSLN+ tumour cells in vitro, including the primary tumour cells from ovarian cancer patients." (PMID 39136096, 2024). "The high expression of mesothelin in ovarian cancer, particularly serous subtypes, makes it an attractive target for immunotherapies." (PMID 38667465, 2024). "Mesothelin is overexpressed in various solid tumors, such as lung, pancreatic, and ovarian cancers, and is shown to contribute to cancer cell proliferation, migration, and survival." (PMID 38396817, 2024). "We find that MSLN-CAR T cells effectively eliminate ovarian cancer tumor cells and stem-like cells in vitro, and this cytotoxic function is dependent on high expression levels of MUC16 on the tumor cell membrane." (PMID 38637885, 2024). "Mesothelin (MSLN) is usually expressed in normal mesothelial cells; however, it is overexpressed in pancreatic cancers, ovarian cancers, and mesothelioma as well." (PMID 39835140, 2024). "Two phase I clinical trials (NCT01469793/NCT02751918) evaluated a novel anti-mesothelin ADC in platinum-resistant ovarian cancer." (PMID 38539161, 2024). "In phase I of a clinical trial (NCT03198546), one patient with recurrent stage III ovarian cancer received two intraperitoneal infusions of anti-mesothelin CAR-T cells engineered to secrete IL-7 and CCL19 (anti-MSLN-7x19 CAR-T)." (PMID 38667465, 2024). "There have been several clinical trials for ovarian cancer treatment using CAR‐T targeting the MSLN antigen." (PMID 39136096, 2024). "MSLN has been further validated as a potential ovarian cancer target through the engineering of several recombinant immunotoxins." (PMID 40836974, 2024). "A phase I clinical trial was conducted on advanced HCC/PC/ovarian carcinoma patients with glypican-3 (GPC3) or MSLN expression (NCT03198546)." (PMID 38727261, 2024). "Mesothelin, a tumour differentiation antigen, has been shown to be overexpressed in human ovarian cancer." (PMID 36166071, 2023). "In our study, we applied the LCAR-M23 technology to genetically modify autologous peripheral blood T cells to enable recognition and elimination of ovarian cancer cells with high expression of MSLN." (PMID 36166071, 2023). "HE4 is the most studied urine protein biomarker for ovarian cancer and has been investigated both alone and in combination with other proteins such as mesothelin and in multi-biomarker panels with promising results." (PMID 36831601, 2023). "MSLN is overexpressed in several types of malignant tumors, including malignant pleural mesothelioma, ovarian cancer, pancreatic adenocarcinoma, and gastric cancer." (PMID 35920319, 2023). "CAR constructs used in CAR M cells principally include CD19 in non-solid tumours, HER 2 in breast and ovarian cancer cells, and mesothelin in ovarian cancer cells." (PMID 38077402, 2023). "Serum mesothelin levels have been found to be elevated in a majority of ovarian cancer patients (67%)." (PMID 36166071, 2023). "Urinary mesothelin levels were shown to be a better indicator of ovarian cancer than serum levels, particularly in early forms (FIGO I and II)." (PMID 37238197, 2023). "A tissue microarray containing 76 human ovarian cancer samples was stained using immunohistochemistry to analyse the expression of MSLN in the samples." (PMID 36166071, 2023). "Their study suggests that MSLN is involved in various pathways involved in suppressing immune activation and promoting chemoresistance, leading to a poor prognosis in ovarian cancer." (PMID 37238197, 2023). "Among the 76 samples analysed, 72 (94.7%) were MSLN-positive, confirming that MSLN was widely expressed in human ovarian cancer samples." (PMID 36166071, 2023).
ovarian carcinoma (continued). "Notably, high mesothelin levels have been associated with chemoresistance and poor survival in epithelial ovarian carcinoma, leading to ongoing clinical trials evaluating the safety and efficacy of mesothelin-targeted drugs in platinum-resistant ovarian cancer." (PMID 37569592, 2023). "Clinically, few trials investigating CAR T-cell treatments for ovarian cancer are under way, with common targets including MSLN, FSHR, MUC16, and HER2." (PMID 36166071, 2023). "PET imaging using a 64Cu- or 89Zr-labeled monoclonal antibody against mesothelin as well as therapeutical usage of antibody-drug conjugate treatment has shown promising results in pancreatic and/or ovarian cancer." (PMID 37614665, 2023). "Several CAR-T cell clinical trials targeting Mesothelin+ (MSLN) ovarian cancer (OC) have been undertaken." (PMID 36717905, 2023). "initiated a Phase I clinical investigation to evaluate the safety and applicability of these CAR-Ts in individuals with ovarian cancer (proficient in the expression of glypican 3 or mesothelin), as well as other advanced solid tumors (NCT03198546)." (PMID 38146364, 2023). "Urine analysis of women with early stages of ovarian cancer showed increased levels of mesothelin in 42% of cases and in 75% of women with advanced stages of cancer." (PMID 37238197, 2023). "The mesothelin and protein CA-125 interaction plays an important role in the implantation of ovarian cancer cells into the peritoneum wall." (PMID 37792745, 2023). "In 2016, Tanyi and colleagues reported the results of a Phase I clinical investigation (NCT02159716) assessing the tumoricidal efficacy of 2nd-generation mesothelin-redirected CAR-Ts intravenously administered to six individuals with ovarian cancer." (PMID 38146364, 2023). "MSLN-specific IgG antibodies were identified in the serum of patients with advanced mesothelioma and ovarian cancer." (PMID 37901248, 2023). "In vitro and in vivo studies have confirmed that LCAR-M23 has a targeted effect on MSLN-expressing human ovarian cancer cells." (PMID 36166071, 2023). "For example, CAR M showed anti-tumor effects on leukemia cells with luciferase gene expression or ovarian cancer cell line HO8910 expressing high mesothelin in-vivo." (PMID 38017494, 2023). "Mesothelin (MSLN) is a cancer‐associated antigen that is overexpressed in malignancies such as mesothelioma, pancreatic and ovarian cancer." (PMID 37040900, 2023). "Mesothelin-specific CAR T-cells have also been evaluated in three patients with epithelial ovarian cancer." (PMID 36829563, 2023). "In ovarian cancer, the interaction between mesothelin and CA125 promotes the metastasis of ovarian cancer cells and stromal tumors, indicating that this combination has a tumor-promoting effect." (PMID 37670338, 2023). "MSLN is highly expressed in mesothelioma, lung cancer, pancreatic cancer, breast cancer, ovarian cancer, and other cancers." (PMID 37359558, 2023). "Next, we examined the expression of MSLN using a pair of ovarian cancer cell lines A2780 and A2780-DDP (cisplatin-resistant) by western blot analysis." (PMID 35692779, 2022). "Different cellular surface antigens have been identified in ovarian cancer as possible targets for ADCs with the FRα and mesothelin representing the most investigated." (PMID 36046840, 2022). "The tumor antigen mesothelin is also frequently overexpressed in ovarian cancer compared to normal tissues, making it a viable target for the diagnosis or the treatment of ovarian cancer." (PMID 35406552, 2022). "We explored the top 50 co-expression genes positively or negatively correlated with MSLN expression in ovarian cancer." (PMID 35692779, 2022). "Both the transgenic strains shed human mesothelin into the serum, similarly as in human mesotheliomas and in patients affected by ovarian cancer: serum human mesothelin can be used as a blood-based surrogate of tumor burden." (PMID 36136517, 2022).
ovarian carcinoma (continued). "MSLN expression is known to be positive in pancreatic adenocarcinoma (82%), mesothelioma (85%), and ovarian cancer (70%)." (PMID 36434635, 2022). "Here, we found that the high expression of MSLN in ovarian cancer was positively correlated with the degree of immune infiltration of Th17 cells, DCs, and NK cells." (PMID 35692779, 2022). "The highest prevalence of mesothelin was found in ovarian carcinomas and mesotheliomas, with higher expression being correlated with advanced tumor stages and higher rates of metastasis." (PMID 35326701, 2022). "An ovarian cancer cell line, Ovcar-8, reported to express MSLN, and recombinant mesothelin (rMSLN) were used as the controls for MSLN expression." (PMID 36009489, 2022). "Mesothelin (MSLN) is broadly overexpressed in many solid tumors including mesothelioma, lung adenocarcinomas and ovarian cancer while remains at a low level on mesothelial cells." (PMID 36569859, 2022). "Based on such biological insights, ERC/mesothelin has become a molecular target for the treatment of mesothelioma, pancreatic cancer, and ovarian cancer." (PMID 35565327, 2022). "It is also very interesting that studies on the correlation between the expression of MSLN in ovarian cancer and survival rate have opposite findings." (PMID 35692779, 2022). "Here, we explore the expression of MSLN in ovarian cancer cisplatin-resistant cells, and in ovarian cancer patients with different sensitivity to various chemotherapy drugs." (PMID 35692779, 2022). "Some promising antigens have been identified including CD138 which is expressed in multiple myeloma and a variety of solid tumors, Trop 2 expressed on the cell surface of most solid tumors and mesothelin expressed in pancreatic and ovarian cancers." (PMID 36348391, 2022). "The authors found that free CA125 promoted ovarian cancer cell migration and tumour metastasis by binding with MSLN, which reduced DKK-1 expression and activated the SGK3/FOXO3 pathway." (PMID 35565412, 2022). "The literature provides limited and conflicting immunohistochemical data regarding MSLN expression and its prognostic impact on ovarian cancers." (PMID 35565412, 2022). "Mesothelin overexpression in ovarian cancer cells also had a similar effect and correlated significantly with MMP-7 expression." (PMID 35326701, 2022). "Mesothelin (MSLN) overexpression (OE) is a frequent finding in ovarian carcinomas and increases cell survival and tumor aggressiveness." (PMID 35162954, 2022). "In one study, a splice variant of soluble mesothelin, named the soluble megakaryocyte-potentiating factor (SMRP), was found in the sera of patients with ovarian carcinoma." (PMID 35565412, 2022). "Mesothelin expression has been identified in many solid tumors, most robustly in mesothelioma, epithelial ovarian cancer, and pancreatic adenocarcinoma, but also in lung and uterine malignancies as well as cholangiocarcinoma." (PMID 35326701, 2022). "In this study, we detected the overexpression of MSLN in ovarian cancer using database analysis and tissue-array staining." (PMID 35692779, 2022). "Researchers used human iPSC-derived NK cells to construct CAR-NK cells targeting mesothelin to treat ovarian cancer." (PMID 36032149, 2022). "In summary, we used a large amount of TCGA database, GTEx database and GEO database information to establish the correlation and function of MSLN in ovarian cancer." (PMID 35692779, 2022). "We found that compared with normal tissues, MSLN was highly expressed in 18 kinds of tumors including ovarian cancer using a pan-cancer analysis." (PMID 35692779, 2022). "The high expression of MSLN was significantly correlated with the decrease of overall survival at the histologic subtype of in ovarian cancer (Endometrioid, p=0.00033; Serous, p=0.0023)." (PMID 35692779, 2022). "Since chemo-resistance in ovarian cancer is a key issue in clinical practice, we also explore the correlation of MSLN and chemo-resistance." (PMID 35692779, 2022).
ovarian carcinoma (continued). "We then focused on the expression of MSLN in ovarian cancer by exploring the TCGA databases and GEPIA2 databases." (PMID 35692779, 2022). "Mesothelin (MSLN) is a cell-surface glycoprotein that is highly expressed in several tumor types, including pancreatic cancer, ovarian cancer, and malignant pleural mesothelioma." (PMID 35326605, 2022). "Another interesting early phase I trial is recruiting mesothelin+ CRC and ovarian cancer patients for treatment with mesothelin-targeting CAR-T cells that secrete PD-1 Nbs." (PMID 35205776, 2022). "Since our research group is focusing on ovarian cancer studies, we aimed to analyze the significance of MSLN in diagnosis, clinical prognosis and chemotherapy resistance of ovarian cancer to provide novel directions for our future work." (PMID 35692779, 2022). "Mesothelin was first discovered while attempting to identify novel cell surface markers in ovarian cancer by isolating antibodies that are reactive with the surface of these cells." (PMID 35326701, 2022). "We used TCGA ovarian cancer cohort to further analyze the relationship between MSLN and immune checkpoints." (PMID 35692779, 2022). "CA-125 binds to mesothelin, a membrane-bound glycoprotein on mesothelial cells, and mediates the binding of ovarian cancer MCSs to mesothelial cells." (PMID 35574025, 2022). "In a phase I study of patients with unresectable pancreatic or platinum-resistant ovarian cancer, 31 ovarian cancer patients had strong staining for mesothelin." (PMID 36618922, 2022). "Mesothelin (MSLN) is a glycosylphosphatidylinositol-linked protein that is overexpressed in different tumor types, including ovarian cancer (OC) and mesotheliomas, and variably impacts the patient’s prognosis." (PMID 35162954, 2022). "The treatment of ovarian cancer cells with metformin, an anti-diabetic drug that also shows anti-cancer properties, reduced mesothelin expression." (PMID 35326701, 2022). "The high expression of MSLN was also significantly correlated with the decrease of overall survival at different clinical stages of ovarian cancer (Stage 1, p=0.13; Stage 2, p=0.14; Stage 3, p=0.02; Stage 4, p=0.001) (D−G)." (PMID 35692779, 2022). "MSLN was positively correlated with immunosuppressive genes in ovarian cancer, such as LGALS9, CD276, TMIGD2, CD200, TNFRSF14, and human leukocyte antigen (HLA)-related families including HLA-DRA, HLA-DRB1, HLA-DPA1, HLA-DMA, HLA-E, etc.." (PMID 35692779, 2022). "Previous studies also demonstrated that high MSLN expression was correlated with poor prognosis in other cancer types, including ovarian cancer, biliary cancer, pancreatic AC, lung AC, and triple-negative breast cancer." (PMID 36434635, 2022). "The expression of Renal Carcinoma (ERC)/mesothelin is overexpressed in malignancies such as mesothelioma, pancreatic cancer, and ovarian cancer, and molecular-targeted therapies against ERC/mesothelin have been developed to treat them." (PMID 35565327, 2022). "Up to now, anti-ERC/mesothelin therapies have been tried to treat ovarian cancer, pancreatic cancer, mesothelioma, and hematological malignancies, but not colorectal cancer." (PMID 35565327, 2022). "For instance, Zhen et found that folate receptor 1 (FOLR1) and mesothelin (MSLN) are specifically highly expressed in ovarian cancer cells by screening the GEO database." (PMID 36275669, 2022). "We have also found studies using oncolytic viruses in combination with CAR-T cells for hard-to-treat solid tumors, such as pancreatic and ovarian cancers targeting the mesothelin antigen, and a variety of HER2+ tumors." (PMID 35681646, 2022). "In order to further evaluate the relationship between MSLN and immune cell infiltration in ovarian cancer, we used the GSVA R package to perform the immune cell infiltration analysis from TCGA datasets." (PMID 35692779, 2022).
ovarian carcinoma (continued). "Applying a mouse monoclonal antibody targeting MSLN in mice bearing ovarian cancer cell xenografts significantly suppressed tumor growth and tumor lymphatic drainage." (PMID 33613114, 2021). "On the other hand, mesothelin expression was better prognosis factor in gastric carcinoma, ovarian carcinoma, and mesothelioma." (PMID 33832498, 2021). "Mesothelin (MSLN) is a cell surface glycoprotein expressed at a high level on many malignancies including pancreatic adenocarcinoma, stomach cancer, ovarian cancer and epithelioid mesothelioma." (PMID 34829955, 2021). "In phase I study for mesothelin targeted therapies, 2.4 mg/kg of mesothelin-targeting antibody-based drug administered three times a week showed safety and partial responses in 3 of 10 (30%) patients with platinum-resistant ovarian cancer." (PMID 33832498, 2021). "In the current study, we investigate the role of host MSLN expression in normal peritoneal tissues, MCA formation and ovarian cancer metastasis using an MSLN wild-type (MSLNWT) and knockout (MSLNKO) mouse model." (PMID 34830322, 2021). "Xenograft mouse models were used to detect the effects of CA125 and anti-MSLN on ovarian cancer metastasis in vivo." (PMID 33613114, 2021). "Human MSLN is strongly upregulated in several human malignancies, including mesotheliomas and ovarian cancer, and is a target for anti-cancer therapy." (PMID 34966784, 2021). "Anetumab ravtansine has promising antitumor activity in mesothelin-expressing solid tumors, such as mesothelioma, ovarian cancer, breast cancer, non-small-cell lung cancer, and pancreatic cancer." (PMID 35008346, 2021). "Several ovarian cancer serum biomarkers, such as mesothelin and LRG, were identified in all three biospecimens." (PMID 33413078, 2021). "Anti-MSLN Abs have been generated and are being tested in clinical trials in patients with ovarian cancer." (PMID 34966784, 2021). "The therapeutic effects of anti-MSLN on ovarian cancer growth and metastasis were confirmed in vivo." (PMID 33613114, 2021). "We then initiated a phase 1 clinical trial in advanced HCC/PC/ovarian carcinoma (OC) patients with glypican-3 (GPC3) or mesothelin (MSLN) expression." (PMID 34325726, 2021). "After enrichment, anti-mesothelin-CARs were stably expressed on iPSC-derived NK cells and were functional in a murine model of ovarian cancer." (PMID 33933160, 2021). "A phase I study using mesothelin specific CAR-NK cells to treat epithelial ovarian cancer is ongoing (NCT03692637)." (PMID 34386017, 2021). "The contribution of mesothelin in cancer development and progression is barely understood, with a clearly defined role only in metastatic spread of ovarian cancer." (PMID 33509252, 2021). "Conversely, for the first time, we investigate the impact of host MSLN expression in ovarian cancer metastasis." (PMID 34830322, 2021). "We and others have reported that mesothelin (MSLN) is widely expressed in human cancers; for example, the majority (80–90%) of PC and ovarian cancers and 100% of epithelial mesotheliomas highly express MSLN." (PMID 34577541, 2021). "Our data showed that anti-MSLN can block the reduction of DKK1 mediated by CA125 in ovarian cancer cells." (PMID 33613114, 2021). "So far, NK-92 cells have been tested in preclinical CAR-NK studies targeting AML (directed to CD33), lymphoma (CD19), myeloma (CS1), prostate cancer (EpCAM), breast cancer (Her2), neuroblastoma (GD2), glioblastoma (EGFR) and ovarian cancer (mesothelin)." (PMID 33933160, 2021). "The MV4;11:MSLN cell line generated by lentiviral transduction of MV4;11 cells using human MSLN had high MSLN expression with 132,290 anti-MSLN antibodies bound per cell, which was far greater than OVCAR-3, a MSLN-positive ovarian carcinoma cell line." (PMID 34885074, 2021). "The study in ovarian cancer also showed that MUC16 binds selectively to mesothelin, a glycoprotein normally expressed by the mesothelial cells of the peritoneum." (PMID 34150633, 2021).